PRRC2B (proline rich coiled-coil 2B)
Synonyms: BAT2L; BAT2L1; KIAA0515; MGC10526; LQFBS-1
Tractability: PROTAC: UniProt records ubiquitination sites on it; ubiquitination databases record sites on it; its protein half-life has been measured.
Gene: Protein-coding gene on chromosome 9 (131,373,636 to 131,500,197, forward strand). Ensembl gene ENSG00000288701.
Subcellular location (Human Protein Atlas): Cytosol; Nuclear bodies
Gene Ontology:
Molecular function: protein binding; RNA binding
Biological process: cell differentiation
Genetic constraint (gnomAD): Loss-of-function variants: 61 observed, 223.19 expected, observed/expected ratio (o/e) 0.27, 90% interval 0.22 to 0.34. The upper end of that interval is the gene's LOEUF score, 0.34, which puts it in group 1 of 6, group 1 being the genes least tolerant of losing a copy. Missense variants: 2,776 observed, 2,949 expected, observed/expected ratio (o/e) 0.94, 90% interval 0.91 to 0.97. Synonymous variants: 1,211 observed, 1,178.1 expected, observed/expected ratio (o/e) 1.03, 90% interval 0.98 to 1.08.
Homologues: Orthologues: chimpanzee PRRC2B (99% identical), macaque PRRC2B (98% identical), dog PRRC2B (88% identical), pig PRRC2B (87% identical), rat Prrc2b (86% identical), mouse Prrc2b (85% identical), guinea pig PRRC2B (85% identical), rabbit PRRC2B (85% identical), tropical clawed frog prrc2b (61% identical), zebrafish PRRC2B (46% identical), Caenorhabditis elegans F52G3.1 (10% identical). Paralogues in human: PRRC2C (34% identical), PRRC2A (27% identical).
Diseases named in the same sentence as PRRC2B in open-access papers:
PRRC2B is named in the same sentence as 16 diseases in open-access papers, as found by Europe PMC text mining. Sharing a sentence is not in itself a finding about the gene and the disease. The quoted sentences say what the papers report.
breast carcinoma (1 paper, 2024). "Two of them, PATL1 and PRRC2B were discussed earlier; SENP7 is a marker of poor prognosis in colon cancer; SPAG9 is expressed in a variety of malignancies and regulated by QKI in lung cancer; UBR5 promotes postsurgical breast cancer lung metastases, and NSD1 exerts tumor suppressive functions." (PMID 39664813, 2024).
cognitive decline (1 paper, 2023). "Conditional knockout of PRRC2B in cerebral endothelial cells alleviates hypoxia‐induced cognitive decline by supplying a remodeling system and regulating cerebral blood flow." (PMID 37395402, 2023). "Therefore, this study aimed to illustrate the proline‐rich coiled‐coil 2B (PRRC2B)‐mediated mechanisms of hypoxia‐induced cognitive decline." (PMID 37395402, 2023). "In addition, conditional knockout of PRRC2B in endothelial cells promotes hypoxia‐induced vascular remodeling and cerebral blood flow redistribution, thus alleviating hypoxia‐induced cognitive decline." (PMID 37395402, 2023).
congenital heart disease (1 paper, 2025). A heart disease that is present at birth. "Our recent work highlighted a novel function of PRRC2B associated with congenital heart disease." (PMID 40869184, 2025). "Two heterozygous loss-of-function mutations of the PRRC2B gene in patients with congenital heart disease are reported to manifest symptoms of pulmonary vein atresia and mitral regurgitation and stenosis, underscoring the connection between PRRC2B and cardiovascular development and disorders." (PMID 40869184, 2025). "Importantly, analysis of clinical data on PRRC2B mutations in 3740 probands with congenital heart disease indicated a significant association with atrial septal defect." (PMID 40869184, 2025).
glioblastoma (1 paper, 2024). The most malignant astrocytic tumor (WHO grade IV). "In addition, we validated the regulation of APA in PRRC2B by PTBP1 in siRNA-knockdown and overexpression experiments followed by RNA-sequencing in two glioblastoma cell lines." (PMID 39188787, 2024).
injury (1 paper, 2023). Damage inflicted on the body as the direct or indirect result of an external force, with or without disruption of structural continuity. "The results of our study provide strong evidence of the function of PRRC2B‐mediated m6A modification in hypoxia‐induced cerebral vascular physiological changes and the potential target for treating hypoxia‐induced brain injury." (PMID 37395402, 2023).
Splenomegaly (1 paper, 2023). Abnormal increased size of the spleen. "The pathological analysis also revealed that PRRC2B cKO mice did not have splenomegaly under hypoxic conditions." (PMID 37395402, 2023).
thymus cancer (1 paper, 2023). A primary or metastatic malignant neoplasm involving the thymus. "Because PRRC2B is highly expressed in cancer cells such as large B cell lymphoma (DLBC), thymus cancer (THYM), and Wilms’ tumor, these ASOs can be applied for potential anti-cancer treatment, which deserves future investigation in biological or disease-relevant models." (PMID 37125639, 2023).
Wilms tumor (1 paper, 2023). An embryonal neoplasm characterized by the presence of epithelial, mesenchymal, and blastema components. "PRRC2B is highly expressed in fast-proliferating tumor cells such as Wilms’ tumor, and its high expression is tightly associated with poor overall survival of patients." (PMID 37125639, 2023).
cancer (2 papers, 2019 to 2023). A tumor composed of atypical neoplastic, often pleomorphic cells that invade other tissues. "Although understudied at the mechanistic level, PRRC2B has been linked with various human cancers." (PMID 37125639, 2023). "Our results suggest that PRRC2B promotes cell proliferation by facilitating the translation of CCND2 mRNA, which encodes the D-type cyclin facilitating G1/S transition in cancer and stem cells." (PMID 37125639, 2023).
tumor (2 papers, 2023 to 2024). "Therefore, understanding the function of PRRC2B may shed light on translational regulation with relevance to tumor cell proliferation and human diseases." (PMID 37125639, 2023).
PRRC2B also shares sentences with these, for which no sentence is quoted: colon cancer (1 paper); leprosy (1); lung carcinoma (1); Mitral regurgitation (1); myelofibrosis (1); Patent ductus arteriosus (1).